ROR1 (ROR family WNT receptor 1)
Diseases named in the same sentence as ROR1 in open-access papers (continued):
Sharing a sentence is not in itself a finding about the gene and the disease.
tumor (continued). "In chronic lymphocytic leukaemia (CLL), a distinct expression of ROR1 on tumour cells has been identified, and ROR1 is currently one out of six markers recommended internationally for refining the diagnosis of CLL." (PMID 38310345, 2025). "An associated depletion of CD68‐positive macrophages upon the addition of anti‐ROR1 CAR T‐cells showed that CAR T‐cell‐mediated cytotoxicity was extended to cells involved in the immune component of the tumor model microenvironment." (PMID 40249196, 2025). "The WNT/ROR1 signaling pathway axis is crucial for tumor progression, resistance to therapy and cell proliferation, driving malignant behaviors in cancer cells." (PMID 39551787, 2024). "In this study, we performed a broad immunohistochemistry (IHC) analysis of ROR1 protein expression using a validated anti-ROR1 monoclonal antibody in several tumor types." (PMID 38791952, 2024). "ROR1 prevalence via immunohistochemistry (IHC) in formalin-fixed paraffin-embedded (FFPE) tumour tissue samples have been widely described in multiple solid tumour indications using various antibodies (Ab)." (PMID 39495778, 2024). "In CLL patients, these trials demonstrated a reduction in the number of tumor cells and cirmtuzumab was found to be safe and effective in targeting ROR1." (PMID 39551787, 2024). "ROR1, a receptor similar to tyrosine kinase, exhibits increased expression in tumor tissues while showing minimal expression in normal tissues." (PMID 38622705, 2024). "2A2-short-tandem induced T cell-mediated killing of ROR1-positive MDA-MB-231 tumor cells with a potency (EC50) of 189 pM and efficacy (Emax) of 86.2%." (PMID 38455046, 2024). "Success of these new drugs depends on the selection of relevant indications based on ROR1 tumour prevalence, staining heterogeneity, and subcellular localization, among other parameters." (PMID 39495778, 2024). "ROR1 supports tumor cell survival by inhibiting apoptosis, while its overexpression drives uncontrolled proliferantion." (PMID 39551787, 2024). "NBE-002, a next-generation ADC that targets ROR1, is the result of conjugation between huXBR1-402 humanized antibody with anthracycline PNU-159682 and binds to the immunoglobulin domain of human ROR1 and inhibit tumor cell growth." (PMID 39551787, 2024). "CLL patients show ROR1-positive tumor cells in the blood, however, 5% of the reported cases had a very low expression of ROR1." (PMID 39551787, 2024). "Pathologists assessed the percentage of tumor cells in each case that were positive for ROR1 and the intensity of staining." (PMID 38791952, 2024). "We did not observe an apparent correlation between baseline expression level of ROR1 and the magnitude of anti-tumor response." (PMID 38408999, 2024). "Given ROR1’s role in promoting tumor development, anti-ROR1 therapies represent a promising approach in hematological malignancies." (PMID 39551787, 2024). "They demonstrated that ROR1 depletion suppresses tumor growth, recurrence after chemotherapy, and metastasis in PDAC." (PMID 38846943, 2024). "First, we confirmed the presence of ER, HER2, and ROR1 proteins on each tumor cell line through flow cytometry analysis." (PMID 38167105, 2024). "There is evidence suggesting that the STAT3 pathway is an important target of ROR1 that can mediate the temporary effects of ROR1 expression in tumor cells and can also promote long-term effects through positive feedback pathways." (PMID 38791952, 2024). "The results showed that ROR1-CAR-T cells had strong anti-tumour activity within 3 d in a dose-dependent manner." (PMID 38475858, 2024). "By blocking ROR1 signaling, these therapeutical approaches can disrupt critical pathways that are essential for tumor cell development and survival." (PMID 39551787, 2024). "The resulting modified ROR1-CAR maintained both target-specific cytolytic activity in vitro as well as persistent anti-tumor functionality in an in vivo xenograft model." (PMID 38464203, 2024).
tumor (continued). "Unlike our 5A1 VHH that does not bind mouse ROR1, the R11 paratope recognizes both human and mouse ROR1 and can be used to assess on-target-off-tumor toxicity in mice." (PMID 38455046, 2024). "Histologic findings from other tumor types showed low overall ROR1 expression that ranged between 0.98% and 13.5% of cases." (PMID 38791952, 2024). "The data shows no unspecific toxicity whereas before the clinical study, these CAR T cells had good response in human tumor xenograft models with ROR1-positive cells." (PMID 39551787, 2024). "The system was used to evaluate the anti-tumour effect of ROR1CAR-T cells composed of a ROR-1-specific single-chain antibody, an IgG4-Fc-derived hinge, the CD28TM domain, and 4-1BB-CD3ζ or CD28-CD3ζ signaling modules." (PMID 38475858, 2024). "Preclinical studies have demonstrated that CAR T cells targeting ROR1 are effective in eliminating tumor cells in vitro and animal models, with early-phase clinical trials assessing their safety and efficacy in humans." (PMID 39551787, 2024). "ROR1 is commonly expressed during embryonic development, but its expression is virtually tumor-specific in adults." (PMID 39796666, 2024). "In contrast, bystander killing of ROR1-negative T-47D only occurred when co-mixed with MDA-MB-231 and was delayed by about 35 hours (measured using the delta in IC50VIABILITY between the ROR1+ and ROR1- tumor cells in the mixture)." (PMID 38455046, 2024). "In IHC, we see a shift to ROR1 positive cells from normal exocrine tissue to the primary tumor as well as the peritoneal metastasis." (PMID 38846943, 2024). "Overall, PDX histologic types showed similar patterns of ROR1 expression as the patients’ tumor types already discussed." (PMID 38791952, 2024). "Concerning the primary tumor of PDAC as well as in the peritoneal metastasis we see a clear positivity for ROR1 in the morphologic tumor cells." (PMID 38846943, 2024). "Exploratory analysis of ROR1 protein expression by IHC in 8 patients with pre-treatment biopsies or paraffin blocks revealed all tumor specimens expressed some level of ROR1." (PMID 38408999, 2024). "The depletion of ROR1 in PDAC suppresses tumor growth, recurrence after chemotherapy, and metastasis." (PMID 38846943, 2024). "Bi-specific T cell engagers (BiTEs) targeting ROR1 are designed to bind both CD3 on T cells and ROR1 on tumor cells, using the immune system’s specificity like CAR T cell therapies." (PMID 39551787, 2024). "Receptor tyrosine kinase-like orphan receptor 1 (ROR1) is a tumour target currently used for the development of novel therapeutic modalities, such as antibody-drug conjugates, chimeric antigen receptor T-cell therapies, and others." (PMID 39495778, 2024). "The geometric arrangement of the ROR1 binding moieties impacts the release of IFNγ from T cells and their capacity to kill tumor cells in a ROR1 dependent fashion." (PMID 38455046, 2024). "When STAT3 is silenced, it results in reduced expression of both Wnt5a and ROR1, leading to increased apoptosis in tumor cells." (PMID 39551787, 2024). "In some cases, patients with MM have a poor outcome after different lines of treatments and develop organ damage thus is important to develop new products that can specifically target tumor cells, by binding to different receptors, like ROR1." (PMID 39551787, 2024). "The expression of ROR1 is associated with poor outcome in DLBCL and other several malignancies due to its importance in tumor cell survival, migration and metabolism." (PMID 39551787, 2024). "For determining the prevalence of staining for each tumor type, a case was considered positive if >1% of its tumor cells showed ROR1 staining." (PMID 38791952, 2024). "In vitro and in vivo NSCLC models, ROR1-CAR T cells maintained their anti-tumour activity, cytokine secretion, and proliferation." (PMID 38475858, 2024). "Following chemotherapy, lncRNA DLEU2 and ROR1 were enhanced in BC tumor cells, coupled with the expression of CSCs, EMT-related genes, and BMI1." (PMID 38296962, 2024).
tumor (continued). "Of note, our ROR1 IHC prevalence results are lower than the results presented by another study performed via FC where ROR1 tumour membrane median positivity for MCL was 56%; DLBCL 50%; FL 28%; and AML 36%." (PMID 39495778, 2024). "We also sought to investigate the impact of hum-VHH-2-LC and the benchmark R11-scFv-1 on the induction of markers of activation and exhaustion on T cells upon co-incubation with ROR1+ tumor cells." (PMID 38455046, 2024). "Further, we identified that WNT5B mRNA and protein correlate with the receptor ROR1 in primary tumours." (PMID 38689429, 2024). "The combination treatment of venetoclax and anti-ROR1 therapy would likely avoid resistance, since it is unlikely that the same tumor cell, hit by two different drugs exploiting two different mechanisms, will be able to survive." (PMID 39551787, 2024). "Zilovertamab vedotin (ZV) is an antibody–drug conjugate (ADC) that binds ROR1 and delivers a microtubule cytotoxic payload to tumor cells." (PMID 38792015, 2024). "Malignant cells use ROR1 expression to promote survival, proliferation and migration, processes normally active in embryonic cells, but redirected by cancer cells to support tumor growth and metastasis." (PMID 39551787, 2024). "High-affinity ROR1 CAR T cells evinced superior proliferation and cytokine production in response to tumor cells with low ROR1 expression as compared to 2A2 scFv based CAR T cells." (PMID 38090558, 2023). "Among the 42 patients with LUAD, 34 (81%) were positive for both Rif and Ror1 in tumor cells, indicating that Rif and Ror1 are highly expressed in LUAD tissues." (PMID 37703992, 2023). "We observed that after several successive tumor-cell in vitro challenges, ROR1.ICOS.OX40ζ continued to proliferate, produce pro-inflammatory cytokines, and induce cytotoxicity against ROR1+ cell lines in vitro with enhanced potency." (PMID 37719008, 2023). "In conclusion, IGFBP5 increases GBM invasion and promotes tumor growth through the ROR1/HER2-CREB signaling axis." (PMID 36949068, 2023). "To study the roles of Ror1 and Rif in tumor development in vivo, we generated Ror1- or Rif-KO PC9 cells by using the CRISPR-Cas9 system and injected them subcutaneously into nude mice." (PMID 37703992, 2023). "Of note, ROR1- and EpCAM-positive lEVs were barely detectable in healthy controls, suggesting their tumor specificity." (PMID 37430307, 2023). "Several studies have provided evidence for the relationship between the PI3K/AKT signaling pathway and the role of ROR1 on tumor cell progression and invasiveness." (PMID 36873868, 2023). "Several studies have demonstrated that tyrosine kinase-like orphan receptor (ROR1) is known to overexpress in triple-negative breast cancer (TNBC) cells and is associated with increased tumor cell proliferation." (PMID 37190185, 2023). "Pre-treatment with oxaliplatin and cyclophosphamide induced a pro-inflammatory tumor microenvironment and enhanced secretion of CCL5, CXCL9, CXCL10, and CXCL16 by tumor-infiltrating macrophages, leading to enhanced ROR1-CAR-T cell infiltration." (PMID 36949946, 2023). "Together, our work reveals a new role for ROR1/STAT3 signaling in tumor heterogeneity and inflammation in OC." (PMID 37400436, 2023). "Of note, ROR1-high tumor cells were enriched after chemotherapy and displayed a partial EMT-like phenotype with a higher capacity for tumor growth, metastasis formation and therapy resistance compared to ROR1-low tumor cells." (PMID 37430307, 2023). "Using various ROR1+ tumor cell lines as target cells, the short version of the hinge domain conferred the highest cytotoxicity and the greatest proliferative capacity on CAR T cells." (PMID 38090558, 2023). "Overexpression of tyrosine kinase-like orphan receptor 1 (ROR1) is supposed to be involved in ES tumor cell migration and invasiveness." (PMID 36983330, 2023).
tumor (continued). "Recognition of EpCAM or B7-H3 on ROR1+ tumor cells activated the synthesis of a transcription factor that, in turn, promoted the transcription of the ROR1 CAR gene." (PMID 36873868, 2023). "This review briefly describes the biological functions of ROR1 and its relevance as a tumor therapeutic target, as well as the architecture, activity, evaluation, and safety of some ROR1 CAR-T cells used in basic research and clinical trials." (PMID 36873868, 2023). "The immune response triggered by the vaccine entailed the production of INF-γ and anti-ROR1 antibodies, inhibited tumor growth, and improved mice survival." (PMID 36873868, 2023). "Overall, the authors concluded that ROR1-CAR T cells were effective at penetrating a tumor mass and killing tumor cells." (PMID 38106674, 2023). "Wnt5a expression was also enriched in OC samples and was found in the OC tumor microenvironment of visceral adipose cells, whereas ROR1 expression was detected in human adipose cells." (PMID 37400436, 2023). "It has also been found that SETD8 can promote tumour cell growth and metastasis through the receptor tyrosine kinase ROR1." (PMID 36934248, 2023). "Silk sericin-coated FeNPs (SS-FeNPs) were recently synthesized for tumor-targeted delivery of ROR1 siRNA to treat TNBC." (PMID 37190185, 2023). "This is the first study on the effects of a small molecule ROR1 inhibitor alone on MCL tumor cell survival and signaling." (PMID 36297673, 2022). "A total of seven days after the T-cell injection, the mice that received either a high or low dose of ROR1 Hinge CAR-T-cells controlled the tumor growth significantly compared to the untreated mice." (PMID 35892876, 2022). "When the mice were sacrificed on day 38 post-tumor engraftment, those mice that received ROR1 Hinge CAR-T-cell treatment had significant lower tumor weight compared to the untreated mice." (PMID 35892876, 2022). "Humoral and cellular immune responses and anti-tumor effects of these fusion proteins were evaluated using two different syngeneic murine ROR1+ tumor models." (PMID 36497309, 2022). "A phase I clinical study was designed to assess the safety and anti-tumor effects of ROR1-targeted CAR-T cells in ROR-positive NSCLC (NCT02706392)." (PMID 35720364, 2022). "F i-CAR-T cells released measurable levels of anti-PD-1 payload with 5 h of binding to ROR1 on tumor and enhanced the cytotoxic effects at challenging 1:10 E:T ratios." (PMID 35659040, 2022). "The significant tumor suppression effect against the untreated mice was persistent up till 28 days in both groups of mice that received ROR1 Hinge CAR-T treatment." (PMID 35892876, 2022). "The mice that received ROR1 Hinge CAR-T exhibited superiority in controlling tumor growth compared to the mice that received the mock T-cells or the untreated mice." (PMID 35892876, 2022). "The data also indicated that combining the ROR1 inhibitor with drugs targeting other dysregulated pathways contributes to an increased anti-tumor effect." (PMID 36297673, 2022). "Co-culture of F i-CAR-T cells with ROR1 + PD-L1 + tumor cell lines demonstrated average production of 4 pM of anti-PD-1 scFv, with expression maintained over time as assessed by ELISA." (PMID 35659040, 2022). "In this study, we constructed a CAR targeting ROR1, which has been reported to be expressed at very low levels on some human tissue but aberrantly expressed on various tumor cells." (PMID 35892876, 2022). "To bolster potency, we developed a F i-CAR construct capable of IL-2-mediated, NFAT-induced secretion of anti-PD-1 single-chain variable fragments (scFv) within the tumor microenvironment, following ROR1-mediated activation." (PMID 35659040, 2022). "The oncofetal protein, receptor tyrosine kinase-like orphan receptor 1 (ROR1), is considered as a promising target for cancer therapy due to its overexpression on many types of tumor cells with low expression in normal adult tissues." (PMID 36497309, 2022).
tumor (continued). "Our next-generation of ROR1-targeting inducible armored CAR platform enables the release of an immune stimulating payload only in the presence of target tumor cells, enhancing the therapeutic activity of the CAR-T cells." (PMID 35659040, 2022). "This approach aims to ensure that secretion of anti-PD-1 scFvs from transgenic T cells only occurs in the TME following engagement with ROR1 on tumor cells." (PMID 35659040, 2022). "Consistently, when the mice were sacrificed 29 days after the engraftment of tumors, the ROR1 Hinge CAR-T-treated mice had a smaller tumor compared to the untreated group." (PMID 35892876, 2022). "Previous clinical trials for zilovertamab selected the dose of zilovertamab considering the ROR1 surface level on circulating tumour cells." (PMID 35456672, 2022). "The ability of CS-E to function as a tumor promoter likely depends on the expression level of CS-E partner proteins such as N-cadherin, ROR1, and DKK1." (PMID 35712490, 2022). "Our results showed that immunization of the mice with fusion proteins containing both the TT peptides and Fc fragment induced a potent anti-tumor CTL response against ROR1+ tumor cells." (PMID 36497309, 2022). "The aim of this study is preclinical evaluation of various ROR1 fusion proteins as novel cancer vaccines in a fully syngeneic mouse tumor model." (PMID 36497309, 2022). "This study explores the sequence, sub-cellular localisation and expression of various transcript variants of ROR1 and ROR2 in healthy human tissues and tumour samples." (PMID 36289823, 2022). "ROR1 and ROR2 transcript variant expression was analysed in 33 different tumour types profiled by TCGA." (PMID 36289823, 2022). "These are autologous T cells engineered to carry receptors specific for tumor antigens, e.g., CD19 or ROR1, thus directing the T cell towards the tumor cell." (PMID 33445713, 2021). "A recent study demonstrated that GR increased tumor heterogeneity and metastasis through ROR1 in breast cancer." (PMID 34400618, 2021). "On day 5 after tumor cell injection, we adoptively transferred pentanoate-treated or untreated ROR1-CAR T cells and monitored T cell engraftment as well as tumor response." (PMID 34210970, 2021). "In this study, tumor cell death in vitro after incubation with an ROR1 inhibitor (KAN0441571C) was compared in ROR1+ CLL cells obtained from patients before and after developing clinical resistance to ibrutinib." (PMID 35844694, 2021). "Studies showed that ROR1 CAR-T therapy effectively killed MDA-MB-231 in microphysiologic 3D tumor models and generated a 20- to 30-fold increase in cancer cell apoptosis." (PMID 33670942, 2021). "Together, these results show that pentanoate and butyrate treatment of murine and human ROR1-specific CAR T cells augments their anti-tumor function in vitro and in vivo." (PMID 34210970, 2021). "In the CLL patients, CAR-T cells had marked expansion in the blood, infiltrated tumor sites (bone marrow compartment), and eradicated ROR1+ CLL cells in the bone marrow." (PMID 34332618, 2021). "Overall, tMUC, αvβ3, TEM8, and ROR1 have been successfully targeted by CAR T cells, which will hopefully stimulate intense research into other tumor-specific or tumor-associated antigens that can be targeted by immunotherapy." (PMID 33670942, 2021). "This tumour specific expression has made ROR1 a promising cancer drug target, leading to several ROR1 targeting therapies being developed." (PMID 34763666, 2021). "It has been robustly evidenced that suppression of TGF-βR signaling improves the anti-tumor activities of receptor tyrosine kinase-like orphan receptor 1 (ROR1)-specific CAR-T cells toward TNBC." (PMID 34321099, 2021). "CAR-T therapy against ROR1 in the presence of TGF-β showed reduction in tumor lysis and cytokine production." (PMID 33670942, 2021).